AR (androgen receptor)
Diseases named in the same sentence as AR in open-access papers (continued):
Sharing a sentence is not in itself a finding about the gene and the disease.
metastatic disease (continued). "The expression of all of the tested biomarkers in cancer cells significantly differed between non-metastatic and metastatic disease, except for AR." (PMID 33920263, 2021). "Bennett et al102 examined CAG repeat length in the AR gene in 151 AA and 168 CA PCa patients, finding AA men had significantly less mean CAG repeats (19.8 vs 21.9), and men with shorter CAG repeats were more likely to have metastatic disease." (PMID 33599076, 2021). "A representative example of a late metastatic driver is AR, which is very rarely found truncal to matching metastatic tumors of the same patient and is never detected in the matching primary tumors." (PMID 34771455, 2021). "Frequency of HiF 1beta and MMP9 positive cells significantly differed between non-metastatic and metastatic disease in epithelium only and AR positive cells significantly differed between non-metastatic and metastatic disease in stroma only." (PMID 33920263, 2021). "Moreover, a possible relation between AR/HER2 and tumor invasion/recurrence/metastatic disease have been reported." (PMID 33287150, 2020). "Furthermore, our study showed benefit of the combination in AR-expressing CRPC cells, a situation also found in patients with advanced metastatic disease that are progressive on ADT." (PMID 31635359, 2019). "Importantly, overexpression of a number of AR-Vs, including AR-V7 and AR-V3, has been reported in 20–40% of CRPC patients, with the figure rising further in metastatic disease." (PMID 31006810, 2019). "Current PC therapies prevalently target the functions of androgen receptor (AR) and may only be effective within short time periods, beyond which the majority of PC patients progress to castration-resistant PC (CRPC) and metastatic disease." (PMID 30828298, 2019). "Concerning PCa, it has been identified as AR regulated (and repressed via NKX3–1), whereas in the absence of AR it is up-regulated and present in metastatic disease." (PMID 29757368, 2018). "Of the 287 patients with LV metastatic disease on the trial who were treated with ADT + AR blocker on either arm, had DNA available, and did not receive concurrent docetaxel, 147 inherited the adrenal-permissive genotype, and 140 inherited the adrenal-restrictive genotype." (PMID 39286977, 2024). "Since the androgen receptor (AR) plays a pivotal role in the development and progression of PCa, androgen‐deprivation therapy (ADT) targeting AR signalling has become the mainstay systemic treatment for patients with locally advanced, biochemically recurrent and metastatic disease." (PMID 38214432, 2024). "However, it is important to note that a higher expression of miR-205-3p was found in metastatic tumors versus non-metastatic tumors and, particularly, in the AR-negative cohorts." (PMID 38339416, 2024). "Moreover, lack of AR nuclear expression was more prominent in both primary and metastatic tumor lesions from castrated TripleTg mice." (PMID 38336745, 2024). "Also in metastatic diseases, there is a significantly increased frequency of VEGF positive lymphocytes related to a cytoplasmic AR ≥ 20% and the frequency of MMP9 positive macrophages was significantly increased regardless of the percentage of AR positive neoplastic epithelial cells." (PMID 33920263, 2021). "Therefore, VEGF is a candidate to be blocked and controlled and to prevent the activation of the androgen receptor (AR)/phosphatidylinositol 4-phosphate 5-kinase type-1 alpha (PIP5K1α)/AKT/MMP-9/VEGF signaling axis required for cell survival and invasion of metastatic tumors." (PMID 31921634, 2019).
metastatic disease (continued). "Four miRNAs (miR-193b-5p, miR-223-3p, miR20a-5p, and miR-328-3p) were up-regulated in AR-positive metastatic tumors versus AR-negative non-metastatic tumors, and one miRNA (miR-489-3p) was up-regulated in AR-positive non-metastatic tumors versus AR-negative metastatic tumors." (PMID 38339416, 2024). "Specific expression of pMET and nuclear β-catenin with a lack of nuclear AR and SYN expression was observed in both prostate and lung metastatic tumor cells, confirming the double-null cell properties of mCRPC in castrated TripleTg mice." (PMID 38336745, 2024). "Additional immunostaining on the metastatic tumor was positive for GATA3, androgen receptor and estrogen receptor, but negative for progesterone receptor." (PMID 38831459, 2024). "Our study has for the first time shown a difference in AR, VEGF, MMP9, HiF 1beta and Ki67 positive cell levels in the stroma and neoplastic epithelium of OSCC between non-metastatic and metastatic disease." (PMID 33920263, 2021). "A significant difference in AR, Ki67 and VEGF expression in cancer stroma between non-metastatic and metastatic disease was found." (PMID 33920263, 2021). "The aim of this study was to, for the first time, compare in OSCC the frequency of AR, VEGF, MMP9, HiF1beta and Ki67 between the non-metastatic and metastatic disease." (PMID 33920263, 2021). "Thus, the aim of this study was to compare the frequency of AR, HIF-1 beta, VEGF, Ki67 and MMP9 levels between non-metastatic and metastatic disease in the stroma and epithelium of OSCC." (PMID 33920263, 2021).
bladder cancer (154 papers, 2008 to 2026). "AR has been implicated as a suppressor of immune function in melanoma, prostate, and bladder cancer." (PMID 41486951, 2026). "Loss of GATA3 in a subset of bladder cancer, especially in high-grade tumors, was correlated with higher AR activity in males." (PMID 41228208, 2025). "While AR signaling has previously been linked to bladder cancer progression, our findings provide novel insights by highlighting its specific role in immune modulation and survival outcomes in males." (PMID 40458476, 2025). "Bladder cancer and AR relationship was also examined many times but the studies were conducted regarding only canonical, full-length AR (AR-FL) and AR splice variants (AR-Vs) were overlooked." (PMID 39083104, 2024). "Given these compelling associations, targeting AR has been the focus of several ongoing and upcoming clinical trials, which will likely lead to additional valuable insights into the associations of AR and bladder cancer." (PMID 38398136, 2024). "For example, both clinical and preclinical studies suggest that AR signaling is a reversible cause of therapeutic resistance to multiple bladder-cancer-directed therapies including BCG immunotherapy, radiation, and cisplatin chemotherapy." (PMID 38398136, 2024). "Additional reported mechanistic associations of AR in bladder cancer suggest that AR signaling is truly pluripotent in this disease." (PMID 38398136, 2024). "Multiple observational studies suggest that reduced AR signaling is linked to lower bladder cancer incidence." (PMID 38398136, 2024). "Taken together, most observational clinical data are consistent with preclinical research that links AR signaling to bladder cancer risk." (PMID 38398136, 2024). "Subsequent research into how immunohistochemical AR positivity is associated with bladder cancer stage generally suggests that low-grade and earlier-stage bladder cancers are more likely to express the AR." (PMID 38398136, 2024). "The precise molecular mechanisms responsible for resistance to cisplatin-based chemotherapy in patients with bladder cancer remain elusive, while we have indicated that androgen receptor (AR) activity in urothelial cancer is associated with its sensitivity." (PMID 37762034, 2023). "AR expression in bladder cancer cells is associated with the chemoresistance observed in bladder tumors." (PMID 37666817, 2023). "Meanwhile, AR activation in bladder cancer cells has been associated with induction of resistance to CDDP as well as other chemotherapeutic agents." (PMID 37762034, 2023). "Bladder cancer occurrence and development can be facilitated by AR mutations that affect ligand binding." (PMID 38283839, 2023). "Different studies described that a change in AR expression levels (high or low expression) seems to be associated with a worse outcome and progression of bladder cancer." (PMID 35992775, 2022). "From a tumor biology perspective, the androgen receptor (AR) has been linked to the genesis and progression of bladder cancer." (PMID 36042998, 2022). "Meanwhile, AR activation in bladder cancer cells has been implicated to be associated with chemoresistance." (PMID 34576193, 2021). "In fact, many studies have reported that AR signaling in bladder cancer cases was associated with recurrence and progression of bladder cancer." (PMID 34552102, 2021). "We thus provide evidence to suggest an underlying molecular mechanism responsible for androgen receptor-induced chemoresistance in bladder cancer." (PMID 33652650, 2021). "The number of polyglutamine (CAG) repeats within exon 1 of the AR gene, which is usually associated inversely with its transcriptional activity, was found to be shorter in bladder tumors or patients with bladder cancer than in respective controls." (PMID 32759680, 2020). "Meanwhile, western blotting in surgical specimens showed potential AR isoforms implying the presence of its splice variant(s) in bladder cancer." (PMID 32759680, 2020).
bladder cancer (continued). "Among them, the knock-down of LSD1 was found to effectively repress bladder cancer growth, and this effect was confirmed to be associated with AR activity regulation." (PMID 32781788, 2020). "Neutrophils promoting androgen receptor (AR)/MMP-13 signals are implicated in bladder cancer cell invasion." (PMID 31799175, 2019). "Expression of AR have indicated to have high risk in bladder cancer occasion, but as for recurrence, expression of AR have shown to contribute to longer RFS." (PMID 30961575, 2019). "AR isoforms (i.e., 90 kDa, 60 kDa) were also detected in some of tumor specimens, suggesting the presence of its splice variants in bladder cancer." (PMID 28241422, 2017). "For example, GATA3 expression correlated with a loss of ERβ as well as with AR/ERα overexpression in bladder cancer." (PMID 28005163, 2017). "Earlier investigators have shown that a variety of AR gene alterations are important in the development of bladder cancer, such as allelic loss and gene mutation." (PMID 26347776, 2015). "To find a new and better target, we focused on AR as its function has been linked well in other urological tumors, including prostate and bladder cancer." (PMID 26304926, 2015). "In this study, we analyzed 2710 bladder cancer samples to find out whether the amount of androgen receptor in tumor cells is linked to patient outcomes." (PMID 41463239, 2025). "The role of an anti-AR agent enzalutamide has been linked to autophagy in bladder cancer cells." (PMID 40486871, 2025). "Another group identified AR-v19, a novel splice variant of AR, in bladder cancer." (PMID 40486871, 2025). "Thus, there are some intriguing associations in our current understanding of sex bias in bladder cancer: AR signaling and T-cell exhaustion, LOY (and KDM5D demethylase loss) and T-cell exhaustion, and sex-dependent demethylase (KDM6A) gene loss." (PMID 38398136, 2024). "Moreover, the role of androgen receptor (AR) in prostate and bladder cancer invasion linked to ADAR2 has been identified." (PMID 37369946, 2023). "AR-ERK activation may thus be associated with chemoresistance via downregulating BXDC2 expression in bladder cancer." (PMID 33652650, 2021). "The combination of risk factors of prevalence in men such as smoking and AR signaling could explain the higher incidence of bladder cancer in men than in women." (PMID 33919565, 2021). "However, underlying mechanisms of how AR and related signals regulate bladder cancer outgrowth still need to be elucidated." (PMID 28241422, 2017). "Indeed, several AR co-regulators have been implicated in the modulation of bladder cancer cell growth." (PMID 28241422, 2017). "However, the underlying mechanisms of how AR signals regulate bladder cancer growth remain far from fully understood." (PMID 26342199, 2015). "Prevention: Given the association of androgen receptor (AR) signaling with bladder carcinogenesis and the likely role of the AR in the substantial male sex bias in bladder cancer, anti-androgen monotherapies may have a future role in bladder cancer prevention." (PMID 38398136, 2024). "The androgen receptor (AR) is important in the development of both experimental and human bladder cancer, yet the role of AR in bladder cancer growth and progression is less clear, with the literature indicating that more advanced stage and grade disease are associated with reduced AR expression." (PMID 38539529, 2024). "Thus, KDM6A has tumor suppressor function, and, as an X-linked gene, it may be an important factor of the male bladder cancer sex bias, which potentially acts in concert with AR/hormonal factors." (PMID 38398136, 2024). "Meanwhile, androgen-mediated androgen receptor (AR) signaling has been implicated in the promotion of urothelial tumorigenesis, which may be a reason for a substantially higher risk of bladder cancer development in men than in women, as well as urothelial tumor progression." (PMID 37762034, 2023).
bladder cancer (continued). "Meanwhile, androgen receptor (AR) signaling has been implicated in the induction of urothelial tumorigenesis, which may clearly explain the male dominance in the incidence of bladder cancer." (PMID 34576193, 2021). "Indeed, androgen receptor activation has been implicated in the induction of urothelial tumorigenesis, which may clearly explain the male dominance in the incidence of bladder cancer, as well as tumor progression (reviewed in 9, 10)." (PMID 33796076, 2021). "Interestingly, this correlation was lost in men with higher grades of cancer (grade 3 and 4), which may be due to the AR loss-of-function during the progression of bladder cancer." (PMID 32781788, 2020). "It has also been reported that AR-mediated T-cell exhaustion was more pronounced in male T cells than in female T cells in melanoma and bladder cancer." (PMID 41486951, 2026). "Potential downstream effectors of AR that modulate cisplatin sensitivity in bladder cancer have been additionally identified." (PMID 40486871, 2025). "AR signaling promotes bladder cancer development and progression, potentially explaining sex-specific differences in bladder cancer incidence and outcomes." (PMID 40458476, 2025). "An increase or a decrease in cisplatin cytotoxicity via inactivation (e.g., anti-androgen treatment, AR knockdown) or overexpression of AR in bladder cancer cells has been confirmed in more recent studies." (PMID 40486871, 2025). "Supportive of this finding, in a cohort of 10,720 male patients with bladder cancer, patients who received 5α-reductase inhibitors, which decrease the AR activity by reducing DHT levels, exhibited improved disease-specific survival." (PMID 41228208, 2025). "AR expression was more common in male (25.9%) than in female (16.2%, p < 0.0001) bladder cancer patients." (PMID 41463239, 2025). "Five additional studies have immunohistochemically determined the expression of AR in 40, 88, 71, 60, and 132 cases of bladder cancer." (PMID 40486871, 2025). "As shown in various other types of non-neoplastic and malignant cells, androgens induce the expression, nuclear translocation, and transcriptional activity of AR in bladder cancer cells." (PMID 40486871, 2025). "Considering also the potential role of AR as a therapeutic target and its potential predictive role for cisplatin resistance, AR is a marker of high interest in bladder cancer that should be further investigated in clinical studies." (PMID 41463239, 2025). "Meanwhile, AR activation was shown to reduce the expression of CD44 known to involve cell-cell interactions and cell adhesion/migration, suggesting the protective role of AR in bladder cancer." (PMID 40486871, 2025). "In bladder cancer cells, AR activity was positively and inversely correlated with the expression of Rab27b and the amount of intracellular BCG, respectively." (PMID 40486871, 2025). "demonstrate that androgen receptor (AR) targeting in bladder cancer enhances NK cell tumor-killing efficacy through reduced PD-L1 expression." (PMID 40852728, 2025). "Functional studies have shown reduced tumor growth and EMT measured by the expression of E-cadherin, ß-catenin, and N-Cadherin in AR-suppressed bladder cancer cells in in vitro and in vivo models." (PMID 41463239, 2025). "Silencing of AR-v19 in bladder cancer lines resulted in a decrease in cell viability and increases in apoptosis and the expression of related molecules, such as cleaved poly(ADP-ribose) polymerase (PARP)." (PMID 40486871, 2025). "Androgen activation of Wnt/β-catenin signaling is linked to tumor progression, with AR promoting nuclear translocation and interaction with T-cell factor (TCF) in bladder cancer cells." (PMID 40458476, 2025). "Meanwhile, dihydrotestosterone (DHT) was shown to be able to induce the development of BBN-mediated bladder cancer in whole-body AR knockout male mice, suggesting the involvement of the androgen-mediated non-AR pathway in urothelial tumorigenesis." (PMID 40486871, 2025).